HOXD9 (homeobox D9)
Diseases named in the same sentence as HOXD9 in open-access papers (continued):
Sharing a sentence is not in itself a finding about the gene and the disease.
thymoma (3 papers, 2020 to 2022). A neoplasm arising from the epithelial cells of the thymus. "Bisulfite pyrosequencing in 46 TEN and 20 paired thymus tissues revealed higher promoter methylation of G protein subunit gamma 4 (GNG4), growth hormone secretagogue receptor (GHSR), homeobox D9 (HOXD9) and spalt like transcription factor 3 (SALL3) in TC than in thymoma." (PMID 35409405, 2022).
astrocytoma (2 papers, 2011 to 2024). "Hypermethylation of CpG islands in promoter regions has been reported for many genes, including the HOXC and HOXD cluster genes associated with HOXD9 in human astrocytomas." (PMID 21600039, 2011).
non-small cell lung carcinoma (2 papers, 2020 to 2023). A group of at least three distinct histological types of lung cancer, including non-small cell squamous cell carcinoma, adenocarcinoma, and large cell carcinoma. "We also identified an inverse correlation between ITF2 and HOXD9 expression, revealing that Non-small cell lung cancer (NSCLC) patients with lower expression of HOXD9 had a better overall survival rate." (PMID 32224864, 2020).
pancreatic cancer (2 papers, 2022 to 2024). "Another study showed that SCNN1A upregulation by homeobox D9 (HOXD9) induced cell proliferation and migration in pancreatic cancer cells." (PMID 36139696, 2022). "Interestingly, a recent study explored the role of homology cassette D9 (HOXD9) and sodium channel epithelial cell 1α subunit (SCNN1A) in pancreatic cancer (PC) progression." (PMID 39511608, 2024).
rheumatoid arthritis (2 papers, 2011 to 2024). A chronic, systemic autoimmune disorder characterized by inflammation in the synovial membranes and articular surfaces. "One of the 5′-HOXD genes, HOXD9, is elevated in synovial cells of rheumatoid arthritis patients." (PMID 38308324, 2024).
thyroid cancer (2 papers, 2023 to 2024). "The findings demonstrated that HOXD9 expression was elevated in most tumor tissues in comparison to normal tissues, and that the downregulation of HOXD9 expression in Thyroid Carcinoma (THCA) tissues was statistically significant." (PMID 37974228, 2023).
anaplastic astrocytoma (1 paper, 2011). "However, HOXD9-positive cells were observed in both anaplastic astrocytoma and GBM tissues." (PMID 21600039, 2011).
Arthritis (1 paper, 2024). Inflammation of a joint. "There is increasing evidence that HOXD9, one of the 5′-HOXD genes, has a role in development of normal joints in early stages and the pathological process of arthritis." (PMID 38308324, 2024).
Cirrhosis (1 paper, 2022). A chronic disorder of the liver in which liver tissue becomes scarred and is partially replaced by regenerative nodules and fibrotic tissue resulting in loss of liver function. "Consistent with previous studies, HOXD9 was significantly associated with prognosis of NAFLD patients in this analysis, indicating that HOXD9 may be an effective clinical therapeutic target for NAFLD of HCC with cirrhosis." (PMID 36397165, 2022). "Compared to non-NAFLD of HCC patients with cirrhosis, GNG4, EPCAM, SPARCL1, DGKK, and SLC39A4 were down-regulated and HOXD9 was up-regulated in NAFLD of HCC patients with cirrhosis." (PMID 36397165, 2022).
clubfoot (1 paper, 2024). The most common congenital deformation of the foot, occurring in 1 of 1,000 live births. "It has been reported that the development of clubfoot involves various genes, such as PITX1, HOXD9, and TBX4, thereby emphasizing the intricate nature of genetic contributions to this condition." (PMID 38858754, 2024).
colon cancer (1 paper, 2021). "In this study, we constructed a 6-gene signature (ITLN1, HOXD9, TSPAN11, GPRC5B, TIMP1 and CXCL13) prognostic stratification system based on the colon cancer invasion-related genes, and evaluated the stability and accuracy of the model." (PMID 33579281, 2021).
colorectal tumor (1 paper, 2020). "The ectopic expression of HOXD9 promoted the invasion metastasis in cells of the colorectal tumor by induction of EMT in vitro and vivo." (PMID 32281284, 2020). "Taken together, our results reported for the first time that high expression of HOXD9 could enhance the formation of aggressive characteristics of colorectal tumor cells." (PMID 32281284, 2020).
cyst (1 paper, 2018). A sac-like closed membranous structure that may be empty or contain fluid or amorphous material. "In addition Hoxc9,10,11−/− Hoxd9,10,11−/− mice, with homozygous mutation of six Hox genes, showed highly penetrant severe cyst formation, while mice with fewer Hox genes mutations also showed cysts but with lower penetrance." (PMID 29679048, 2018).
cystic kidneys (1 paper, 2018). "For example, Hoxc9,10,11−/− Hoxd9,10,11−/− mutants showed highly penetrant severely cystic kidneys, while several other Hox mutation combinations produced cystic kidneys with lower penetrance." (PMID 29679048, 2018). "Grossly cystic kidneys were observed in all surviving Hoxc9,10,11−/− Hoxd9,10,11−/− mutants (age 3–6 weeks) (Y’, BB’)." (PMID 29679048, 2018). "Additionally, in mice uniformly sacrificed at 2 months of age, 10–15% of the Hoxa9,10,11−/− Hoxc9,10,11+/−, and Hoxa9,10,11+/− Hoxc9,10,11−/−, and triple heterozygote Hoxa9,10,11+/− Hoxc9,10,11+/− Hoxd9,10,11+/− mice showed grossly cystic kidneys (X’, Y’)." (PMID 29679048, 2018).
cystic teratoma (1 paper, 2024). "The most interesting findings of this study are amplifications of EVX2, HOXD13, HOXD12, HOXD11, HOXD10, and HOXD9 on a 41.6 kb segment of 2q31.1 in all nine mature cystic teratomas." (PMID 38907278, 2024). "In summary, amplifications of EVX2, HOXD13, HOXD12, HOXD11, HOXD10, and HOXD9 on 2q31.1, NDUFV1 on 11q13.2, and RPL10, SNORA70, DNASE1L1, TAZ, ATP6AP1, and GDI1 on Xq28 were found in all nine mature cystic teratomas in this study." (PMID 38907278, 2024).
diabetic kidney disease (1 paper, 2024). Progressive kidney disorder caused by vascular damage to the glomerular capillaries, in patients with diabetes mellitus. "Our findings highlighted that HOXD9/APOC1 was a key player in causing podocyte injury in diabetic kidney disease and led to macrophage M1 polarization through the NF-κB signaling pathway." (PMID 39511608, 2024). "However, few studies have been reported on HOXD9 in diabetic kidney disease." (PMID 39511608, 2024).
Ewing sarcoma (1 paper, 2017). A small round cell tumor that lacks morphologic, immunohistochemical, and electron microscopic evidence of neuroectodermal differentiation. "We and others have shown that the posterior HOXD genes, HOXD9, HOXD10, HOXD11, and HOXD13 are overexpressed by Ewing sarcoma and that the promoters of these genes are devoid of the repressive H3K27me3 mark and highly enriched with the MLL-mediated H3K4me3 mark." (PMID 27888797, 2017).
metastatic cancer (1 paper, 2019). A carcinoma which has spread from the original site of growth to another anatomic site. "To validate our findings in vivo, we examined HOXD9 expression in regional lymph nodes and metastatic cancer tissues from two patients." (PMID 31547840, 2019). "Furthermore, we examined the expression of HOXD9 and RUFY3 in serial sections of lymph node metastatic cancer tissues from two patients." (PMID 31547840, 2019).
MRKH syndrome (1 paper, 2023). "Several genes have been implicated in MRKH syndrome, such as HOXA7, HOXA9–13, HOXD9–13, and WNT4." (PMID 37240886, 2023).
muscular dystrophy (1 paper, 2012). Muscular dystrophy (MD) refers to a group of more than 30 genetic diseases characterized by progressive weakness and degeneration of the skeletal muscles that control movement. "Firstly, HOXD9 gene regulate muscle cell growth, proliferation, differentiation and innervation, it can be speculated that these gene abnormalities cause muscle denervation, resulting in muscular dystrophy, or muscle fiber type and quantity of muscle leads to the malformation." (PMID 22520331, 2012).
neuroblastoma (1 paper, 2012). Neuroblastoma (NB) is the most common solid, extracranial childhood tumor. "In this study, we show that individual induction of HOXD8, HOXD9, HOXD10 or HOXD12 in neuroblastoma cells is able to recapitulate RA-induced differentiation phenotype." (PMID 22879880, 2012). "Together, these findings demonstrate distinct functions of HOXD proteins in regulation of neuroblastoma cell proliferation, with only HOXD3, HOXD8, HOXD9, HOXD10 and HOXD12 proteins being able to recapitulate the G1 arrest phenotype induced by RA." (PMID 22879880, 2012). "Notably, the four human HOXD proteins (HOXD8, HOXD9, HOXD10, HOXD12) with both anti-growth and differentiation-inducing activities in neuroblastoma cells correspond to the Drosophila Hox proteins abd-A (HOXD8) and Abd-B (HOXD9, HOXD10, HOX12) that are responsible for specifying the abdomen." (PMID 22879880, 2012).
osteoarthritis (1 paper, 2025). A noninflammatory degenerative joint disease occurring chiefly in older persons, characterized by degeneration of the articular cartilage, hypertrophy of bone at the margins and changes in the synovial membrane. "Several other genes are implicated in DDH but currently have a sparse association with human osteoarthritis in the literature, including BMS1, HOXD9, TBX4, TENM3, and PAPPA2." (PMID 41019141, 2025). "Several other genes implicated in DDH and/or FAI but with a sparse association with human osteoarthritis in the literature, including BMS1, HOXD9, TBX4, TENM3, PAPPA2, and HOXB9, should be further investigated to elucidate their role in osteoarthritis development." (PMID 41019141, 2025).
osteosarcoma (1 paper, 2023). A usually aggressive malignant bone-forming mesenchymal neoplasm, predominantly affecting adolescents and young adults. "Previous research suggested that HOXD9 could influence the progression of osteosarcoma malignancy via the PI3K/AKT/mTOR pathway." (PMID 37974228, 2023).
ovarian carcinoma (1 paper, 2015). A malignant neoplasm originating from the surface ovarian epithelium. "Of 11 confirmed GWAS susceptibility loci identified for ovarian cancer, one contained a statistically significant eQTL association (HOXD9) at a FDR≤0.1." (PMID 26391404, 2015). "We observed an interaction between the region containing rs2857532 and the HOXD9 promoter in two different epithelial ovarian cancer cell lines." (PMID 26391404, 2015). "HOXD9 expression was detected in ∼80% of ovarian cancer cell lines and all normal ovarian epithelial cell lines, but was absent in the normal fallopian tube epithelial cell lines." (PMID 26391404, 2015). "Here the authors use expression quantitative train locus analysis to identify candidate genes and functionally characterise them, identifying a role for HOXD9 in ovarian cancer." (PMID 26391404, 2015). "These transcription factors do not bind the reference allele and thus represent candidate transcription factors that may function upstream of rs2857532 to modulate HOXD9 expression during ovarian cancer development." (PMID 26391404, 2015). "Using quantitative PCR with reverse transcription (RT–qPCR) analysis we quantified expression of HOXD9, CDC42 and CDCA8 in ovarian cancer cell lines (N=14) and ovarian (N=6) and fallopian (N=3) epithelial cells." (PMID 26391404, 2015).
renal agenesis (1 paper, 2018). Renal agenesis (RA) is a form of renal tract malformation characterized by the complete absence of development of one or both kidneys (unilateral RA or bilateral RA respectively), accompanied by absent ureter(s). "Conversely, renal agenesis was rarely observed in Hoxc9,10,11−/− Hoxd9,10,11−/− mutants (1 out of a total of 25 mutants examined), and nephrogenesis continued through E18.5 (Q’)." (PMID 29679048, 2018).
thyroid (1 paper, 2023). "We also evaluated the level of tumorigenesis and metastasis in the orthotopic murine thyroid model with ATC cells containing si-HOXD9." (PMID 37974228, 2023). "Overall, these results demonstrate that the silencing of HOXD9 can prevent lung metastases in an orthotopic murine thyroid model." (PMID 37974228, 2023). "Targeting HOXD9 may offer a novel therapeutic approach for this aggressive thyroid malignancy." (PMID 37974228, 2023).
triple-negative breast carcinoma (1 paper, 2021). An invasive breast carcinoma which is negative for expression of estrogen receptor (ER), progesterone receptor (PR), and human epidermal growth factor receptor 2 (HER2). "Therefore, our results revealed that miR-205 can target the HOXD9-Snail1 to suppress triple negative breast cancer cell proliferation and chemoresistance." (PMID 33428601, 2021). "miR-205 could function the HOXD9-Snail1 to suppress triple negative breast cancer cell proliferation and chemoresistance." (PMID 33428601, 2021). "Moreover, we proved that miR-205 could target the HOXD9-Snail1 axis to suppress triple negative breast cancer cell proliferation and chemoresistance." (PMID 33428601, 2021).
tumor (30 papers, 2011 to 2025). "The current study suggested that increased expression of HOXD9 is associated with proliferation, invasion, and spread of the tumor and indicates poor prognosis in patients suffering from CRC." (PMID 32281284, 2020). "This indicates that the expression of HOXD9 is positively associated with tumor proliferation." (PMID 37974228, 2023). "Deletion of HOXD9 could inhibit tumor cell proliferation and cause cell cycle G1 arrest, as well as weaken tumor-forming capacity." (PMID 36907878, 2023). "In addition, HOXD9 expression is linked to tumor proliferation, invasion, and distant metastasis." (PMID 36262353, 2022). "A progressive increase in promoter-to-exonic methylation was noted in the paralogous HOXA9 and HOXD9 genes with increasing tumor stage." (PMID 40676709, 2025). "HOXD9 also induced epithelial-to-mesenchymal transition (EMT) in tumour cells, thereby maintaining the invasive potential of cancer cells." (PMID 37225681, 2023). "In parallel, we found that knocking down HOXD9 in vivo dramatically reduced tumor growth and lung metastasis development." (PMID 37974228, 2023). "In summary, knockdown of HOXD9 facilitates proliferation, migration, invasion capacities and also induces apoptosis in 8505c cells, suggesting a tumor suppressive role." (PMID 37974228, 2023). "Studies by various researchers, including our group, have reported that HOXD9 promotes tumour metastasis via EMT alterations." (PMID 37225681, 2023). "The apoptosis rate was significantly higher and cell proliferation and microvascular density were lower when HOXD9 is suppressed in tumor cells." (PMID 37974228, 2023). "Consistent with in vitro findings, the downregulation of HOXD9 in ATC cells impeded tumor growth and lung metastasis in vivo." (PMID 37974228, 2023). "From 1895 metastasis-related genes, they found that the expression of SLC2A1, CDCA8, ATG10, and HOXD9 was higher in HCC tumor tissue whereas the expression of TPM1 was lower." (PMID 37974228, 2023). "Several studies have discovered that interactions between HOXD9 and miRNA can influence tumor proliferation, metastasis, or EMT." (PMID 37974228, 2023). "The western blot results on tumor tissues revealed that silencing of HOXD9 blocked the PI3K/AKT signaling pathway." (PMID 37974228, 2023). "In this work, using pan-cancer perspective profiling datasets from The Cancer Genome Atlas (TCGA) database, we first examined HOXD9 expression in 24 tumor and normal tissues." (PMID 37974228, 2023). "Compared to normal tissues, the expression of HOXD9 was lower in ccRCC tumor tissues of TCGA cohort, while it was higher in ccRCC tumor tissues of ICGC cohort." (PMID 36387262, 2022). "The expression levels of SLC2A1, CDCA8, ATG10 and HOXD9 are higher in tumor samples and lower in normal tissue samples." (PMID 34116652, 2021). "If HOXD9 activates the P105 promoter to induce the expression of the E7 gene, then knockout of HOXD9 will suppress E7 gene expression and restore the tumor suppressor function of RB." (PMID 34572841, 2021). "High expression of HOXD9 has significantly associated with the American Joint Committee on Cancer (AJCC) stages, tumor differentiation, lymph node metastasis, and other serious invasions, and it had a poor prognosis." (PMID 32281284, 2020). "We also observed that the tumor samples had higher expression levels of HOXD9 than the controls, as it has been previously reported." (PMID 32224864, 2020). "The function of the HOXD9 gene in regulating tumor growth and metastasis has attracted limited attention." (PMID 32281284, 2020). "We showed that increased HOXD9 expression is correlated with differentiation (P < 0.001), lymph node metastasis (P < 0.001), tumor size (<10 cm3 vs ≥ 10 cm3, P = 0.001), AJCC stage (I/II vs. III/IV, P = 0.001) and TNM stage (I/II vs. III/IV, P < 0.001)." (PMID 31547840, 2019).